TP53INP1 (tumor protein p53 inducible nuclear protein 1)
Diseases named in the same sentence as TP53INP1 in open-access papers (continued):
Sharing a sentence is not in itself a finding about the gene and the disease.
Parkinson disease (2 papers, 2021 to 2025). A progressive degenerative disorder of the central nervous system characterized by loss of dopamine producing neurons in the substantia nigra and the presence of Lewy bodies in the substantia nigra and locus coeruleus. "This study demonstrated that lncRNA A2M-AS1 reduces oxidative stress and improves Parkinson's disease by regulating TP53INP1-mediated mitophagy through interaction with IGF2BP1 by combining molecular results and results of clinical samples and animal experiments both in vivo and in vitro." (PMID 40111649, 2025). "Here, we addressed the unexplored role of TP53INP1 and of its Drosophila homolog dDOR in the maintenance of neuronal homeostasis under chronic stress, focusing on dopamine (DA) neurons under normal ageing- and Parkinson’s disease (PD)-related context." (PMID 33966044, 2021). "We hypothesized that OM-MSC-derived exosomes, Lnc A2M-AS1, regulate TP53INP1-mediated mitophagy by interacting with IGF2BP1 to reduce oxidative stress and improve the condition of Parkinson’s disease." (PMID 40111649, 2025).
acute pancreatitis (1 paper, 2013). An acute inflammatory process that leads to necrosis of the pancreatic parenchyma. "Originally, TP53INP1 expression is strongly induced in mice with acute pancreatitis in vivo, and also in several cell lines under exposure to various stress agents in vitro." (PMID 24152184, 2013).
age (1 paper, 2019). A temporal measurement of the time period elapsed since an identifiable point in the life cycle of an organism. "Therefore, this study has important significance in detecting TP53INP1 expression and regulation effects in age-related cataract pathogenesis." (PMID 31281592, 2019).
Age-related cataract (1 paper, 2019). A type of cataract (opacification of the lens) that forms during the course of aging. "SUMO-1, SUMOylation, and TP53INP1 were upregulated in lens tissues affected by age-related cataracts." (PMID 31281592, 2019). "We found that the oxidative stress-induced endogenous SUMOylation of TP53INP1 promoted human lens epithelial cell (holed) apoptosis and regulated hLEC antioxidant effects by increasing the stability and transcription of TP53INP1 in age-related cataracts." (PMID 31281592, 2019). "The major unique finding in the present study is that the oxidative stress-induced SUMOylation and consequent stabilization of TP53INP1 promoted LEC apoptosis and decreased LEC antioxidant activity in tissue affected by age-related cataracts." (PMID 31281592, 2019).
allergic rhinitis (1 paper, 2023). Inflammation of the nasal mucous membranes caused by an IgE-mediated response to external allergens. "Studies have demonstrated that TP53INP1 may have an anti-inflammatory role because it can inhibit the nuclear factor-κ B (NF-κB) signaling pathway in patients with allergic rhinitis, but the specific mechanism is largely unknown." (PMID 36776864, 2023).
cardiac hypertrophy (1 paper, 2024). "Furthermore, TP53INP1 silencing considerably alleviated D-gal-induced cardiac hypertrophy, myocardial IL-1β and IL-6 levels, and β-gal-positive cells in the KO mice." (PMID 39511427, 2024).
cataract (1 paper, 2019). Partial or complete opacity of the crystalline lens of one or both eyes that decreases visual acuity and eventually results in blindness. "In the present study, anterior lens capsules of age-related cataract patients were used to assess the potential effects of SUMOylation/deSUMOylation of TP53INP1 in cataract formation." (PMID 31281592, 2019). "Previous to our study, there was no previous investigation into the role of TP53INP1 in cataract development." (PMID 31281592, 2019).
chordoma (1 paper, 2020). Chordomas are rare malignant tumors arising from embryonic remnants of the notochord in axial skeleton. "For instance, Duan and colleagues found that low miR-1 expression in chordoma tissues promoted the proliferation and invasion of tumor cells by upregulation of slug, while miR-155 led to aggressive chordoma phenotype and poor patient survival mainly via regulating SOCS1 and TP53INP1 expression." (PMID 33194623, 2020).
chronic heart failure (1 paper, 2023). "Mir-8485 can also alleviate cardiomyocyte injury in chronic heart failure (CHF) by targeting TP53INP1." (PMID 37250717, 2023).
Cirrhosis (1 paper, 2025). A chronic disorder of the liver in which liver tissue becomes scarred and is partially replaced by regenerative nodules and fibrotic tissue resulting in loss of liver function.
Glucose intolerance (1 paper, 2015). Glucose intolerance (GI) can be defined as dysglycemia that comprises both prediabetes and diabetes. "Glucose intolerance and IR further developed when TP53INP1-deficient mice were fed a HFD, and hyperinsulinemia finally occurred in such experimental conditions with plasma insulin levels twice as high in HFD-fed TP53INP1-deficient as in WT animals." (PMID 25828351, 2015). "In contrast, NAC-treated HFD-fed TP53INP1-deficient mice showed similar metabolic profiles to HFD-fed WT animals (Fig2A and B) indicative of chronic oxidative stress predisposing those mice to systemic IR, hyperinsulinemia, glucose intolerance and therefore T2D." (PMID 25828351, 2015).
lymphoma (1 paper, 2025). A malignant (clonal) proliferation of B- lymphocytes or T- lymphocytes which involves the lymph nodes, bone marrow and/or extranodal sites. "An example of this is TP53INP1, the expression of which has been shown to differentiate lymphomas with EZH2 mutations and BCL2 translocations from other lymphoma subtypes." (PMID 41497400, 2025).
ovarian cancer (1 paper, 2015). A primary or metastatic malignant neoplasm involving the ovary.
pancreatitis (1 paper, 2009). Inflammation of the pancreas. "An over-expression of TP53INP1 has been associated with Bax expression and apoptosis in acinar cells but not in ductal or Langerhans cells in the pancreas of a mouse model of pancreatitis, so we determined TP53INP1 α and β expression in NOD acinar cells." (PMID 19356238, 2009). "Interestingly, immunohistochemical analyses revealed that increased expression of TP53INP1 during the acute phase of pancreatitis was only observed in acinar cells with no staining of Langerhans islets or pancreatic duct cells." (PMID 19356238, 2009).
psoriasis (1 paper, 2023). An autoimmune condition characterized by red, well-delineated plaques with silvery scales that are usually on the extensor surfaces and scalp.
T-cell leukemia (1 paper, 2017). A malignant disease of the T-lymphocytes in the bone marrow, thymus, and/or blood. "miR-93 is up-regulated in PBMCs from adult T-cell leukemia patients, and suppresses the expression of a tumor suppressor protein, tumor protein 53-induced nuclear protein 1 (TP53INP1)." (PMID 28057018, 2017).
tumor (86 papers, 2011 to 2026). "Decreased expression of TP53INP1 in tumor tissues was inversely associated with their expression of miR-125b, significantly lower in poorly differentiated tumors and inversely correlated with the clinical stages in patients with NSCLC." (PMID 26388699, 2015). "TP53INP1 dysregulation has been associated with enhanced tumor survival and resistance to therapy, suggesting that miR-155 suppression of TP53INP1 may provide an additional advantage to VEGF-driven tumorigenesis." (PMID 41345725, 2025). "In addition, high MSI2a expression in tumor cell xenografts was associated with strong TP53INP1 staining." (PMID 32448269, 2020). "Other affected genes are related to apoptosis (Ddx20, Ikbip), integrin-associated signal transduccion (Cd47), stress protein with antioxidant-associated tumor suppressive function (Tp53inp1/Trp53inp1), calcium signaling (Stim1), as well as those related to proliferation and survival (Lin28a)." (PMID 30742662, 2019). "Importantly, using the median or lower decile of TP53INP1 mRNA expression as the cut-off point, Kaplan-Meier analysis showed that low levels of TP53INP1 mRNA expression in tumor tissues were significantly associated with poor patient survival." (PMID 24952595, 2014). "The analysis identified miR‐93‐5p binding sites within the 3′‐UTRs of several key tumor‐associated genes, including PTEN, CDKN1A (p21), TP53INP1, and THBS2." (PMID 41159542, 2026). "These miRNAs are often associated with aggressive tumor phenotypes and poor prognosis, acting by inhibiting tumor suppressor genes such as PTEN and TP53INP1." (PMID 40244378, 2025). "Our bioinformatic analysis identified more than 20 potential miR-1206 targets, including E2F3 (a transcription factor that regulates cell proliferation) and TP53INP1 (a tumor suppressor gene regulating autophagy)." (PMID 38612604, 2024). "For example, the overexpression of circCDYL has promoted apoptosis and inhibited cell proliferation through regulation of the miR-190a-3p/TP53INP1 axis, therefore upregulating the tumor-suppressing TP53INP1 protein in TNBC." (PMID 37736901, 2023). "Some researchers have identified hsa-miR-106a as an oncomiR that targets TP53INP1 in metastatic lung cancer, indicating its involvement in tumor suppression." (PMID 37628602, 2023). "According to a previous study, microRNA-569 expression increased because of 3q26.2 amplification in epithelial cancers, which down-regulated TP53INP1 mRNA expression and enhanced the sensitivity of tumor cells to cisplatin." (PMID 35483343, 2022).
tumor (continued). "MiR-106b was shown to exert its function by targeting TP53INP1, which is a tumor suppressor and autophagy-inducer gene in tumor cells." (PMID 36465388, 2022). "It has been documented that TP53INP1 exerts tumor suppressor function through involvement in cell death, cell-cycle arrest and cellular migration." (PMID 35070952, 2021). "Tumour protein 53‐induced nuclear protein 1 (TP53INP1) is a tumour suppressor, whose expression is down‐regulated in diverse types of cancers." (PMID 33960661, 2021). "TP53INP1 is a tumour suppressor, whose expression is downregulated in different types of cancers from different organs." (PMID 34718338, 2021). "The tumor volume and weight, and tumoral miR‐548n expression were decreased significantly by TCONS_00026334 overexpression, whereas the TP53INP1 and P21 expression increased obviously." (PMID 32986920, 2020). "The effect of SAM to decrease methylation was proved to be beneficial in certain genes (HT-29: DTX1, GATA4, SEZ6L, TP53INP1; SW480: HAAO, TAL1), whose hypermethylation was associated with tumor progression according to the scientific literature." (PMID 32784836, 2020). "Taken together, our study showed that TCONS_00026334 acts as an anti‐tumor and anti‐metastatic gene by regulating the miR548n/TP53INP1 axis in the development of CRC." (PMID 32986920, 2020). "Collectively, these findings suggested that TCONS_00026334 overexpression had the ability to restrain tumor growth in vivo via downregulating miR‐548n to increasing the expression of TP53INP1." (PMID 32986920, 2020). "In the current study, we provided compelling biological data and ex vivo evidence showing that TP53INP1 plays a tumor suppressive role in TNBC." (PMID 32448269, 2020). "Ten days after injecting plasmid, the tumour sizes were obviously smaller in the TP53INP1‐overexpressing group than in the control group." (PMID 29655255, 2018). "On the other hand, recent studies have also demonstrated that TP53INP1 expression is often downregulated or silenced in cancer cells by numerous onco-miRNAs including miR-130b, miR-155, and miR-125b which are present in tumor cells." (PMID 28962647, 2017). "According to recent literature overexpression of miR-155 can strongly reduce TP53INP1 expression in cancers, and inhibition of miR-155 leads to the suppression of tumor growth in vitro and in vivo." (PMID 25823817, 2015). "For example, suppressor of cytokine signaling 1 (SOCS1) and tumor protein 53-induced nuclear protein 1 (TP53INP1) – two validated targets of miR-155 –have been shown to regulate tumor growth, invasion, and metastasis." (PMID 25823817, 2015). "We further revealed that the expression of miR-125b was inversely correlated with the expression level of TP53INP1 in tumor tissues." (PMID 26388699, 2015). "Given that TP53INP1 has been proved to be a direct target of miR-125b, we further evaluated the possible role of TP53INP1 in tumor promoting activity of miR-125b." (PMID 26388699, 2015).